DMKN (dermokine)
Description:
May act as a soluble regulator of keratinocyte differentiation.
Synonyms: ZD52F10; UNQ729
Tractability: Antibody: UniProt places it where antibodies can reach, with high confidence; UniProt predicts a signal peptide or a membrane-spanning region; its Gene Ontology location is reachable by antibodies, with medium confidence. PROTAC: ubiquitination databases record sites on it.
Gene: Protein-coding gene on chromosome 19 (35,497,220 to 35,513,693, reverse strand). Ensembl gene ENSG00000161249.
Subcellular location: Secreted
Subcellular location (Human Protein Atlas): Cytosol; Nucleoplasm; Predicted to be secreted
Pathways (Reactome):
Developmental Biology: Differentiation of Keratinocytes in Interfollicular Epidermis in Mammalian Skin
Gene Ontology:
Molecular function: protein binding
Biological process: cornified envelope assembly
Cellular component: extracellular region
Genetic constraint (gnomAD): Loss-of-function variants: 58 observed, 69.16 expected, observed/expected ratio (o/e) 0.84, 90% interval 0.68 to 1.04. The upper end of that interval is the gene's LOEUF score, 1.04, which puts it in group 4 of 6, group 1 being the genes least tolerant of losing a copy. Missense variants: 593 observed, 608.52 expected, observed/expected ratio (o/e) 0.97, 90% interval 0.91 to 1.04. Synonymous variants: 238 observed, 236 expected, observed/expected ratio (o/e) 1.01, 90% interval 0.91 to 1.12.
Homologues: Orthologues: chimpanzee DMKN (79% identical), pig DMKN (63% identical), dog DMKN (62% identical), mouse Dmkn (55% identical), rat Dmkn (53% identical).
Diseases named in the same sentence as DMKN in open-access papers:
DMKN is named in the same sentence as 11 diseases in open-access papers, as found by Europe PMC text mining. Sharing a sentence is not in itself a finding about the gene and the disease. The quoted sentences say what the papers report.
colorectal cancer (3 papers, 2012 to 2021). A primary or metastatic malignant neoplasm that affects the colon or rectum. "For instance, modified APA patterns have been reported during the progression of colorectal cancer, affecting three genes: dermokine (DMKN), pyridoxal kinase (PDXK), and peptidylpropyl isomerase E (PPIE)." (PMID 29495341, 2018). "Studies have confirmed that the abnormal expression of DMKN is related to skin cancer, pancreatic cancer, colorectal cancer, and other cancers, but no study has shown its role in nervous system tumors." (PMID 33902636, 2021).
pancreatic cancer (3 papers, 2021 to 2024). "The DMKN gene, which harbors five splice variants (α, β, γ, δ, and ε), has been previously studied to suggest that suppressing DMKN-β/γ reduces the invasiveness and migratory capabilities of pancreatic cancer cells, potentially impacting the epithelial-mesenchymal transformation (EMT)." (PMID 38735973, 2024). "Previous studies showed that DMKN contributed to epithelial–mesenchymal transition in pancreatic cancer." (PMID 36944954, 2023). "These are consistent with several studies which have shown that overexpression of DMKN enhances the proliferation and epithelial–mesenchymal transition of pancreatic tumor cells; MyD88 in myofibroblasts can promote macrophage M2 polarization." (PMID 36944954, 2023).
liver fibrosis (1 paper, 2025). "Amongst them was DMKN, encoding for the protein Dermokine, which had recently been identified as a regulator for hepatic stellate cell (HSC) activation, the main cellular players in liver fibrosis." (PMID 39996122, 2025).
melanoma (1 paper, 2024). A malignant, usually aggressive tumor composed of atypical, neoplastic melanocytes. "Moreover, the paper explores potential druggable targets for melanoma patients, including ERK5, CD73, ALDH1A1, PLA1A, and DMKN, which hold promise in addressing diagnostic hurdles and guiding personalized therapeutic decisions." (PMID 39582535, 2024). "Collectively, DMKN and PLA1A present themselves as promising candidates for personalized therapy, shedding light on their multidimensional roles in shaping the melanoma phenotype in tailored treatment strategies." (PMID 39582535, 2024).
periodontitis (1 paper, 2024). An acute or chronic inflammatory process that affects the tissues that surround and support the teeth. "Spatial transcriptomics revealed significant upregulation of ACTB, GSTO1, RAB1B, HBB, DMKN, and CTSZ in basal epithelial cells during periodontitis." (PMID 39769019, 2024).
cancer (3 papers, 2021 to 2025). A tumor composed of atypical neoplastic, often pleomorphic cells that invade other tissues. "Dermokine (DMKN), involved in differentiation of epithelial cells, was the most downregulated gene in post-treatment specimen (group A cancer)." (PMID 41151488, 2025).
tumor (3 papers, 2023 to 2025). "Dermokine and matriptase are involved in epithelial differentiation and inflammation, while tryptase is associated with the tumor microenvironment, which may contribute to carcinogenesis." (PMID 40704599, 2025).
nervous system tumors (1 paper, 2021). "However, a report showing that DMKN can affect the activation of STAT3 and down-stream molecular proteins of the MAPK and PI3K signaling pathways suggests that DMKN may play a role in nervous system tumors through this pathway." (PMID 33902636, 2021).
DMKN also shares sentences with these, for which no sentence is quoted: dysplasia (1 paper); neutropenia (1); skin cancer (1).